RNU6-384P (RNA, U6 small nuclear 384, pseudogene)
Gene: Small nuclear RNA gene on chromosome 20 (31,581,089 to 31,581,192, forward strand). Ensembl gene ENSG00000201770.
Homologues: Orthologues: chimpanzee U6 (99% identical), macaque U6 (95% identical), dog U6 (69% identical). Paralogues in human: RNU6-11P (87% identical), RNU6-37P (87% identical), RNU6-1094P (86% identical), RNU6-15P (86% identical), RNU6-17P (86% identical), RNU6-18P (86% identical), RNU6-30P (86% identical), RNU6-1 (85% identical), RNU6-1025P (85% identical), RNU6-1091P (85% identical), RNU6-12P (85% identical), RNU6-1331P (85% identical), and 1289 more.